CISD2 (CDGSH iron sulfur domain 2)
Diseases named in the same sentence as CISD2 in open-access papers (continued):
Sharing a sentence is not in itself a finding about the gene and the disease.
tumor (continued). "We further performed PDUI analysis of CISD2 and NIT2 in 56 paired samples, and the results also showed that the PDUI value of CISD2 and NIT2 were also significantly lower in LUAD tumor tissues (P = 8.80 × 10−17, P = 2.88 × 10−5)." (PMID 39003419, 2024). "Silencing of CISD2 stimulates apoptosis and uncontrolled autophagy in HCC and increases sorafenib-mediated ferroptosis in tumor cells." (PMID 36759819, 2023). "Therefore, we hypothesize that CISD2, which is primarily located on the mitochondria, might also modulate the β-catenin in response to the activation of Wnt/β-catenin pathway to contribute to tumor carcinogenesis and progression in LSCC." (PMID 27007153, 2016). "This negative association suggests that heightened methylation of these specific CpG sites may lead to downregulation of CISD2 in COAD samples, potentially impacting the tumor microenvironment and patient prognosis." (PMID 37304867, 2023). "Elevated CISD2 and CISD1 proteins have been observed in human epithelial breast cancer cells; inhibiting CISD2 and CISD1 expression results in increased iron accumulation within mitochondria, autophagy activation, and significant reduction of cell proliferation and tumor growth." (PMID 37304867, 2023). "This implies that the 3′UTR length of CISD2 and NIT2 were significantly shorter in LUAD tumor tissues compared with adjacent non-tumor tissues." (PMID 39003419, 2024). "Using TCGA database, the PDUI value of CISD2 and NIT2 were significantly lower in total LUAD tumor tissues compared with adjacent non-tumor tissues (P = 2.01 × 10−55, P = 2.90 × 10−7)." (PMID 39003419, 2024).
neurodegenerative disease (5 papers, 2017 to 2021). A disorder of the central nervous system characterized by gradual and progressive loss of neural tissue and neurologic function. "In cases of advanced cellular insult (e.g., acute CNS trauma or neurodegenerative disease), CISD2 has been shown to influence the mechanisms underlying inflammation and mitochondrial dysfunction." (PMID 30934593, 2019). "The anti-inflammatory effects of CISD2 in microglia eventually augment anti-apoptotic effects, which provides a rationale for the development of potential therapeutic target for neurodegenerative diseases and neurodegenerative dementia." (PMID 33005144, 2020). "CISD2-based anti-inflammatory therapy is a strong candidate for the treatment of neuroinflammation-driven aging and neurodegenerative diseases." (PMID 33005144, 2020). "In the current study, we sought to delineate the roles of CISD2 in non-stressed and advanced inflammation associated with aging, CNS injury, and neurodegenerative disease." (PMID 30934593, 2019). "It is very likely that anti-inflammatory and/or anti-apoptotic therapies based on CISD2 could be used to reduce the effects of aging, neurodegenerative disease, and CNS trauma." (PMID 30934593, 2019). "We therefore postulate that the unique function of curcumin is its ability to elevate injury-attenuated CISD2 expression, thereby protecting against inflammation, mitochondrial dysfunction, and apoptosis during the pathogenesis of TBI, SCI, and neurodegenerative diseases." (PMID 30934593, 2019).
head and neck tumor (1 paper, 2022). "CDGSH iron-sulfur domain-containing protein 2 (CISD2) gene silencing makes resistant head and neck tumor cells sensitive to SSZ-induced ferroptosis by increasing lipid ROS and Fe2+ levels." (PMID 36352396, 2022).
infection (1 paper, 2017). The state of being infected such as from the introduction of a foreign agent such as serum, vaccine, antigenic substance or organism. "Based on the mRNA and protein expression levels in GC cell lines, CISD2 overexpression models were constructed using lentiviral infection." (PMID 28857517, 2017).
lung (1 paper, 2017). "In the second, we explored whether EGR1 or CISD2 expression level would be affected by treatment with hydrogen peroxide in lung ADC cells." (PMID 28928421, 2017). "This upregulation of CISD2 mRNA was also found in our in-house-generated dataset GSE46539, and can be confirmed by an independent RT-qPCR assay using our previously collected lung ADC samples." (PMID 28928421, 2017).
neurodevelopmental disorder (1 paper, 2014). A behavioral and cognitive disorder with onset during the developmental period that involves impaired or aberrant development of intellectual, motor, or social functions. "To examine this gene network specifically in neurodevelopmental disorders, we searched human genetic data for variants within CISD2, PPT1, CLN3 and the other 19 human genes identified by network analysis in humans." (PMID 24705017, 2014).
CISD2 also shares sentences with these, for which no sentence is quoted: deafness (6 papers); Blindness (2); Childhood onset (2); fatty liver (2); genetic disease (2); glioblastoma (2); insulin-dependent diabetes mellitus (2); migraine (2); Peptic ulcer (2); psychiatric disorder (2); sarcopenia (2); steatosis (2); acute myeloid leukemia (1); Age-Related Hearing Loss (1); astrocytoma (1); ataxia telangiectasia (1); autosomal dominant retinitis pigmentosa (1); cardiac interstitial fibrosis (1); Cerebral ischemia (1); essential hypertension (1); Friedreich ataxia (1); heart failure (1); hemochromatosis (1); hyperglycaemia (1); iron overload (1); lysosomal storage disorders (1); metabolic disease (1); myocardial infarction (1); non-small cell lung carcinoma (1); Obesity (1).
A further 8 diseases each share a sentence with CISD2 in 1 paper.